RUNX3 (RUNX family transcription factor 3)
Diseases named in the same sentence as RUNX3 in open-access papers (continued):
Sharing a sentence is not in itself a finding about the gene and the disease.
sarcopenia (1 paper, 2025). Progressive decline in muscle mass due to aging which results in decreased functional capacity of muscles. "In the sarcopenia samples, pathways such as type 2 papillary renal cell carcinoma, EPO-NF-κb pathway, and RUNX3 regulates CDKN1A transcription were significantly enriched." (PMID 41463417, 2025).
scleroderma (1 paper, 2025). Scleroderma is a rare autoimmune connective tissue disorder characterized by abnormal hardening of the skin and, sometimes, other organs. "Based on the expression of each transcription factor, RUNX3 was identified as the key regulator of the scleroderma-specific APCDD1_fibroblast." (PMID 41350567, 2025).
sclerosteosis (1 paper, 2007). "We carried out real-time quantitative reverse-transcriptase PCR (Q-RT-PCR) validation for two genes, SOST (sclerosteosis) and RUNX3 (runt-related transcription factor 3) which each were significantly altered according to the microarray data." (PMID 17634102, 2007).
serous ovarian cancer (1 paper, 2021). "New RUNX3 overexpression models of high-grade serous ovarian cancer (HGSOC) were established and analyzed for phenotypic (IC50 determination, migration, proliferation and angiogenesis assay, DNA damage analysis) and transcriptomic consequences (NGS) of RUNX3 TV1 and TV2 overexpression." (PMID 33530588, 2021).
squamous cell carcinoma (1 paper, 2023). A carcinoma arising from squamous epithelial cells. "In squamous cell carcinoma, enhancer of zeste homolog 2 (EZH2) inhibits RUNX3 (RUNX Family Transcription Factor 3) expression to activate both SETDB1 and ΔNp63α, which drives an aggressive cancer stem cell phenotype." (PMID 38057834, 2023).
Stroke (1 paper, 2014). Sudden impairment of blood flow to a part of the brain due to occlusion or rupture of an artery to the brain. "Runx3 was one of the very few transcripts showing high levels at 2 weeks post-stroke in young rats." (PMID 24672479, 2014).
tubular adenocarcinoma (1 paper, 2012). An infiltrating adenocarcinoma in which the malignant cells form tubular structures. "The lowest and highest Runx3 mRNA expression occurred in poorly differentiated adenocarcinoma group and tubular adenocarcinoma group, respectively." (PMID 23243425, 2012). "In tubular adenocarcinoma group, Hlx, T-bet, and Runx3 expression levels were higher than those of other patient groups, although these indicators were lower than that in healthy control." (PMID 23243425, 2012).
uveitis (1 paper, 2023). An inflammatory process affecting a part of or the entire uvea. "Single-cell analysis supported that CD1c+ DCs in eye fluid of patients with non-infectious uveitis contain also a population that has a gene profile reminiscent of CX3CR1+ DC3s, with relatively higher levels of CX3CR1, CD36, CCR2, and lower levels of RUNX3." (PMID 37042831, 2023).
tumor (387 papers, 2004 to 2026). "Consistently, we observed a higher frequency of deletions in CDH1, which encodes E-cadherin, a critical suppressor of tumor metastasis, and RUNX3, which promotes E-cadherin expression and inhibits EMT, in these patients." (PMID 41002582, 2025). "Epigenetic inactivation of RUNX3 and the prognosis of loss of function of tumor suppressor genes via promoter hypermethylation has been described for RUNX3, an important mediator of the TGF-β signaling pathway." (PMID 40650134, 2025). "Deletion or downregulation of RUNX3 in HCC is associated with increased tumor aggressiveness, vascular invasion, and worse prognosis." (PMID 41002582, 2025). "The methylation of genes such as RUNX3, GSTP1, SHOX2, DKK3, and MLH1 is associated with tumor progression and malignancy, with RUNX3 showing high promoter methylation in NSCLC tissues." (PMID 40136480, 2025). "As the evidence suggests, low expression levels of RUNX3 are generally associated with a poor prognosis, highlighting its role as a tumor suppressor." (PMID 38430423, 2024). "Firstly, RUNX3 pathway signature was positively associated with tumor-infiltrating lymphocytes (TILs) (Spearman’s ρ = 0.53, P < 0.001)." (PMID 38172737, 2024). "RUNX3 plays a role in immunity and has been implicated in both oncogenic and tumor suppressive functions." (PMID 39020437, 2024). "qPCR and immunofluorescence staining showed significantly higher expression of RUNX3 mRNA and protein in liver metastasis, compared with spleen tumor cells, indicating that high RUNX3 expression is associated with metastasis." (PMID 38240752, 2024). "For instance, in papillary thyroid cancer (PTC), hypermethylation at specific CpG sites leading to downregulated RUNX3 expression has been significantly associated with an elevated risk of tumor recurrence." (PMID 38430423, 2024). "As a multifunctional transcription factor, RUNX3 is implicated in diverse signalling pathways and cellular processes, thereby exerting multiple effects on tumour suppression." (PMID 37759525, 2023). "RUNX3 is required for normal liver development, while its loss is associated with hepatocellular carcinogenesis, where it acts as a tumour suppressor." (PMID 37759525, 2023). "The tumor suppressive effect of RUNX3 can be inactivated in several ways (mutations, methylation-related transcriptional silencing, and mis-localization to the cytoplasm)." (PMID 36900240, 2023). "Here, high RUNX3 expression in tumor stroma was shown to be positively associated with poor prognosis." (PMID 36831308, 2023). "Of particular interest, RUNX3 expression in stromal tissue was associated with the density of tumor-infiltrating lymphocytes." (PMID 36900240, 2023). "Epigenetic inactivation of RUNX3 is tightly linked to the early stages of bladder, lung, and gastrointestinal carcinogenesis, suggesting that RUNX3 is a potential tumor-suppressor." (PMID 36831211, 2023). "First, we observed significant downregulation of CD8+ T cells and effector T cells in peripheral blood, spleen, tumor tissue of mice with Runx3 deficiency." (PMID 37189103, 2023). "During the current study, we also found mutations of Smarca4, Runx3 and Cxcr4 in early disseminated tumor cells." (PMID 36424557, 2022). "Another example includes the loss of function mutation in RUNX3 in gastric cancer patients, which was experimentally determined to be unresponsive to TGFβ signaling and causative for the tumor progression." (PMID 36231078, 2022). "The PAM and RUNX3 genes have anti-cancer and tumor suppressor activities, and thus, their loss-of-function is characteristic of gastric and several other types of cancer." (PMID 36202992, 2022).
tumor (continued). "Among the TFs involved in proliferation which are marked by H3K27 methylation, is RUNX3, a member of the runt-related family associated with normal development and neoplasia." (PMID 34884658, 2021). "Upon cancer development, the RUNX3 promoter is hypermethylated, leading to reduced TF activity and loss of tumor suppression activity." (PMID 34367349, 2021). "RUNX3—the gene that encodes for runt-related transcription factor 3—is a known tumor suppressor and is associated with inhibiting the pro-oncogenic effect of TGF-β." (PMID 34298613, 2021). "Methylated RUNX3 copies were significantly associated with tumor size, massive submucosal invasion, and lymph-vascular invasion." (PMID 32224873, 2020). "By contrast, increased CCL5 expression resulting from RUNX3 mutation is associated with more tumor metastasis in the lung." (PMID 32218434, 2020). "In CRC, RUNX3 is taken as a tumor suppressor since its methylation is a significant risk factor for tumor development and high nuclear expression of RUNX3 is associated with better survival." (PMID 32717065, 2020). "Our major finding is that miR-301a deficiency reactivates the immune response in the tumor microenvironment by recruiting cytotoxic T cells through negatively regulating Runx3 expression." (PMID 31122259, 2019). "Runt-domain transcription factor (RUNX3), not only shows oncogenic properties implicated in several major developmental pathways, but also acts as a tumor suppressor that increase apoptosis and reduce cell proliferation." (PMID 31139570, 2019). "This is the first demonstration that miR-301a deficiency enhances CD8+ T cell accumulation by negatively regulating Runx3 that are implicated in the anti-tumor immunity." (PMID 31122259, 2019). "The IHC results show that a higher PIM1 and lower RUNX3 level is associated with advanced T-stage, lymph node involvement and nerve invasion that translates to aggressive tumor behavior." (PMID 29467592, 2018). "Pro-tumorigenic properties like EMT and stem-ness, which are directly linked with tumor metastasis and progression, are suppressed by RUNX3 in YAP expression dependent manner, similar to what we observed in MCF10a cell line." (PMID 29581836, 2018). "There is extensive literature on RUNX3 for various tumor entities and it appears to be causally involved in tumor development." (PMID 29342962, 2018). "It is clear that the tumor suppressor activity of RUNX3 is at least partly associated with its ability to induce p21 expression." (PMID 29467592, 2018). "RUNX3 expression was associated with tumor size (p = 0.039) and poor histological differentiation (p = 0.033)." (PMID 29100342, 2017). "For RUNX3, a growing body of evidence implies that RUNX3 is tightly linked to gastoric development and also acts as a tumor suppressor toward gastoric cancer." (PMID 27294865, 2016). "RUNX3 (Runt-related transcription factor 3), a strong tumor suppressor associated with diverse tumor types, has been suggested to be associated with cancer development through regulating global DNA methylation levels." (PMID 25616342, 2015). "Together, these data indicate that RUNX3 inactivation is a major risk factor in early tumorigenesis and its inactivation contributes to tumor progression via increasing angiogenesis." (PMID 26375442, 2015). "The different modes of RUNX3 inactivation in various tumor types include hemizygous deletion, mutations, hypermethylation, histone modifications and cytoplasmic mislocalization." (PMID 25229459, 2014). "Recently, inactivation or loss of RUNX3 was found closely associated with tumourigenesis and tumour progression." (PMID 24447545, 2014). "High expression of Pim-1 and low expression of RUNX3 were associated with aggressive tumor behavior." (PMID 25551195, 2014). "Our data showed that decreased RUNX3 expression was drastically associated with tumor size, depth of invasion and TNM stage." (PMID 23457532, 2013).
tumor (continued). "On the other hand, lower expression level of RUNX3 is associated with tumor progression and poor prognosis in various cancers." (PMID 24078903, 2013). "Recently, hypermethylation of the RUNX3 promoter region was found to be significantly associated with the presence of lymph node metastases and tumor stage in tongue carcinomas." (PMID 22645611, 2012). "According to previous studies, the overexpression of the fusion protein, Runx1-Runx1t1 causes the downregulation of Csf-1 (a hematopoietic cytokine known to cause activation of microglia) and Runx3 (a tumour suppressor)." (PMID 22697290, 2012). "The methylation of the same genes was also associated with tumor stage RUNX3 (p = 0.040), SCGB3A1 (p = 0.032), SFRP4 (p = 0.033), and DLC1 (p = 0.035)." (PMID 20849603, 2010). "Loss of Runx3 predisposes knockout mice to gastric hyperplasia, indicating a tumor suppressor-like role for this gene." (PMID 18551179, 2008). "RunX3 and Vegf expression were inversely associated and restoration of RunX3 expression in cancer cells inhibited tumor growth and metastasis." (PMID 19412438, 2007). "It has therefore been elucidated that RunX3 is a tumor suppressor of GC associated with the Tgf-β signalling pathway." (PMID 19412438, 2007). "The RUNX family—RUNX1 (Runt-related transcription factor 1), RUNX2 (Runt-related transcription factor 2), and RUNX3 (Runt-related transcription factor 3)—has been implicated in both normal development and oncogenesis, with RUNX3 functioning as a tumor-suppressor gene across multiple malignancies." (PMID 41181710, 2025). "The involvement of WNT5A signaling in cancer stem cell self-renewal, which is potentially associated with tumor initiation and metastasis, suggests that RUNX3 may cooperate with WNT5A to regulate cancer stem property." (PMID 38240752, 2024). "Promoter hypermethylation leading to decreased protein levels has also been documented in EAOC for several other tumor suppressor genes encoding Runt-related transcription factor 3 (RUNX3), E-cadherin (CDH1), the Ras-association domain family of gene 2 (RASSF2), and CDKN2A/p16." (PMID 39062866, 2024). "RUNX3 has been implicated as a tumor suppressor or oncogene in different type of cancers." (PMID 37032358, 2023). "In these tumors, RUNX3 was found to enhance cell proliferation, inhibit apoptosis, and confer drug resistance, indicating that RUNX3 enhances malignant properties associated with the progression of malignancy, such as tumor invasion and metastasis." (PMID 37190031, 2023). "RUNX3 has been implicated in neutrophil/T lymphocyte regulation; its functional loss may increase the risk for UC and facilitate UC-associated tumor growth." (PMID 36140736, 2022). "In a platinum-sensitive OC cohort mostly comprised of patients with HGSC, the combination of CAMK2N1 (calcium/calmodulin dependent protein kinase II inhibitor 1) and RUNX3 (RUNX family transcription factor 3) methylation in tumor specimens was associated with shorter OS and PFS." (PMID 35406435, 2022). "RUNX3 encodes a tumor suppressor which regulates cell growth, survival, differentiation, angiogenesis, and invasion; FILIP1L is a protein that inhibits metastases and chemoresistance; MT1E is a cytoskeleton-modifying protein, involved in cell migration and invasion." (PMID 36499753, 2022). "RUNX3-deficient mice are associated with tumor predisposition in the gastrointestinal tract." (PMID 34831147, 2021).
tumor (continued). "Likewise, it was observed that the loss of RUNX3 gene located at chromosome 1p36.1 triggered tumor development, since this gene serves as a tumor suppressing agent." (PMID 31721911, 2019). "In current study we aimed to evaluate RUNX3 gene methylation and protein expression in only astrocytic origin tumours of different grade to estimate association between methylation frequency and protein expression, as well as evaluate the RUNX3 alteration effect on patient survival." (PMID 31467531, 2019). "Moreover, we show that miR-301a controls tumor metastasis by targeting Runx3/β-catenin, providing an underlying mechanism of miR-301a-mediated tumor promotion in NSCLC cells and during lung tumorigenesis." (PMID 31122259, 2019). "Besides RUNX3 methylation association with tumour grade and patient age we found very strong association between RUNX3 methylation and patient survival what indicates prognostic importance of RUNX3." (PMID 31467531, 2019). "Consequently, they proposed that RUNX3 is a tumor-suppressor gene causally involved in gastric carcinogenesis." (PMID 29201108, 2017). "In addition, the inactivation of RUNX3 in OSCCs due to gene promoter hypermethylation is significantly associated with tumor stage and the presence of lymph node metastases." (PMID 28030842, 2017). "We therefore hypothesised that enrichment of RUNX3 P1 hypomethylated alleles in these tissues might reflect leukocyte recruitment to the premalignant epithelium and/or tumor microenvironment." (PMID 26682246, 2015). "Although the detailed molecular mechanisms underlying the RUNX3 tumor suppressive function are still unclear, several lines of studies have provided the evidence that RUNX3 has an ability to regulate both transforming growth factor beta (TGFβ) and Wnt signaling pathways." (PMID 24709709, 2013). "This region contains several genes including RUNX3, a transcription factor, which has been shown to be frequently deleted or transcriptionally silenced in a number of cancers, and it has been suggested to encode an important tumour suppressor." (PMID 18071362, 2008). "For example, in CD138+ myeloma stem cells, Shh signaling is activated by RARα2 Referring to the contribution of Shh signaling to CSC-associated tumor metastasis, the study has shown that the degradation of Gli by RUNX3-mediated ubiquitination could reduce CSC-associated tumor metastasis in CRC." (PMID 37853437, 2023). "More study is needed to understand the relationship between the RUNX3's involvement in the tumor‐promoting ability and the association of this protein with good clinical outcome, from which we could seek for a possibility to focus on RUNX3 as a therapeutic target in the future." (PMID 37641472, 2023). "In present analysis we demonstrated that RUNX3 is starting to be deregulated from very onset of gliomagenesis at both epigenetic (methylation) and functional (protein expression) levels and these changes are tightly associated with patient age and survival as well as tumour pathological grade." (PMID 31467531, 2019). "Therefore, DNA methylation-mediated silencing of RUNX3 might contribute to the loss of its tumor-suppressive function." (PMID 26512706, 2015). "Some authors advocate a threshold of 1%, however, a lower threshold for ER positivity would necessitate down regulation of ER positive cells in our model that may be consistent with a partial loss of RUNX3 function or alternative mechanism that may represent a biologically different tumor." (PMID 23704974, 2013). "Runt-related transcription factor 3 (RUNX3) acts as a critical tumor suppressor and regulates immune cell function, while its biological role in NK cells remains largely unexplored." (PMID 42023209, 2026).